LEP (leptin)
Diseases named in the same sentence as LEP in open-access papers (continued):
Sharing a sentence is not in itself a finding about the gene and the disease.
Obesity (continued). "In addition to eosinophils, increased proliferation and survival of Th2 cells and ILC2s induced by leptin was observed in mouse models of allergic airway disease and allergic patients with obesity." (PMID 40329860, 2025). "Studies have shown that short sleep duration alters appetite-regulating hormones, reducing leptin and increasing ghrelin levels, which disrupts appetite and subsequently may lead to obesity." (PMID 39940229, 2025). "In some horses leptin concentrations exceed those expected based on the amount of fat due to the presence of obesity‐related leptin resistance, which may act to worsen the existing degree of obesity." (PMID 38984777, 2025). "However, this beneficial effect of leptin appears to be diminished in obese mice, possibly due to leptin resistance in the setting of obesity." (PMID 41200178, 2025). "Due to these complexities, further research is essential to delineate specific obesity phenotypes, clarify leptin’s mechanistic role, and evaluate the potential of leptin sensitizers or other targeted interventions to address obesity-related complications in COPD management." (PMID 40283443, 2025). "In obesity, where leptin levels are elevated due to increased fat mass and leptin resistance, there is a concomitant increase in IL-6 levels, further contributing to low-grade chronic inflammation that characterizes obesity-related diseases like insulin resistance and cardiovascular disease." (PMID 40218903, 2025). "The mechanisms by which Zn contributes to obesity may involve the modulation of leptin and interleukin-6 (IL-6) expression in visceral adipose tissue." (PMID 41459237, 2025). "Additionally, several proteins were linked to metabolic disorders such as obesity, diabetes, and hyperuricemia, including AGRP, LEP, SORT1 and SOD2." (PMID 40242450, 2025). "Therefore, this study aimed to investigate the potential anti-obesity effects of garlic and stevia extracts along with aerobic exercise on hypothalamic leptin and ghrelin receptor mRNA levels, as well as insulin resistance, in obese male Wistar rats." (PMID 40087612, 2025). "Additionally, they differed in hs-CRP and adiponectin/leptin ratio from individuals with obesity cardiometabolically healthy." (PMID 39940942, 2025). "Thus, the insulin-leptin system paradoxically becomes a positive feedback loop or “vicious cycle” in obesity." (PMID 40950761, 2025). "Unexpectedly, this association was stronger at higher BMI, possibly due to weight loss preceding dementia (masking leptin’s protection) and greater leptin variability in obesity, which may explain the inconsistency with prior findings." (PMID 41516046, 2025). "During obesity, adipokines such as leptin and adiponectin are released inappropriately." (PMID 39981087, 2025). "First, hypothyroidism may favor weight gain by reducing the basal metabolic rate; secondly, obesity and increased leptin levels play an immunomodulatory and pro-inflammatory role that triggers autoimmunity." (PMID 40150555, 2025). "Animal experiments confirm that high-fat diet-induced obesity models display abnormal bone metabolism, including trabecular bone structure deterioration and impaired bone formation, observable within a short period, alongside elevated serum leptin levels." (PMID 41246338, 2025). "Leptin and adiponectin levels are particularly altered, and although these hormones can be produced in other organs (such as the skeletal muscle), obesity has a significant effect on these hormone levels, given that they are primarily produced in the white adipose tissue." (PMID 40002337, 2025). "In obesity, this rhythm is blunted, leading to leptin resistance and hyperphagia." (PMID 40650041, 2025). "The changes of leptin and orexin are involved in the pathogenesis of obesity." (PMID 40551883, 2025).
Obesity (continued). "One study linked the anti-obesity effect of GIPR antagonism to leptin sensitivity in the hypothalamus, where genetically or pharmacologically blocking GIPR enhanced the anorexigenic properties of leptin in HFD-fed mice." (PMID 40166681, 2025). "Protein tyrosine phosphatase 1B (PTP1B) is a soluble enzyme that plays an essential role in the regulation of metabolism, specifically in the modulation of leptin and insulin sensitivity, marking it as an interesting therapeutic target for the treatment of type 2 diabetes and obesity." (PMID 40906363, 2025). "At the molecular level, obesity is characterized by altered lipid metabolism, chronic low-grade inflammation, and dysfunction in several key signaling pathways, including those involving insulin, leptin, and adiponectin." (PMID 39974837, 2025). "An association between CAMKK1 and leptin was observed in both controls and individuals with obesity, but not in patients with T2DM." (PMID 40965347, 2025). "Therefore, we believe that identifying, and not assuming, the origin-point of metabolic disruption within the vicious loop (e.g., targeting leptin resistance instead of replacing leptin in “polygenic” obesity), would help improve therapeutic outcomes." (PMID 41573210, 2025). "Leptin has long been recognized as a mediator connecting obesity to BC." (PMID 41409302, 2025). "Based on these findings, the leptin/leptin-R signal pathway could be linked to the pathogenesis of several tumors, especially RCC, in which obesity plays an important role as a causative risk factor." (PMID 41010935, 2025). "As a secondary focus, the present study explored the relationships between key appetite- and obesity-related biomarkers (serum leptin, serum ghrelin, and salivary cortisol) and eating behaviors, as well as their potential regulatory roles in shaping these behaviors." (PMID 41470868, 2025). "To investigate the mediators of interorgan communication, we monitored the blood glucose, serum insulin, serum leptin, and plasma GLP-1 levels in 20-week-old mice, because prolonged increases of these metabolites are known to be associated with the development of obesity." (PMID 40179260, 2025). "Some female-specific characteristics of the leptin-VEGF relationship in obesity have been observed." (PMID 41302116, 2025). "Leptin’s primary role is to regulate energy storage in the body, but its regulation is asymmetric, as it is more effective in replenishing fat storage when it is low than resisting obesity." (PMID 41036146, 2025). "Moreover, systemic factors such as obesity, insulin resistance, and sex hormones strongly influence leptin-DC interactions in vivo." (PMID 41516046, 2025). "While setmelanotide is currently approved only for rare genetic types of obesity, its ability to reduce leptin resistance suggests potential for use in non-genetic forms of obesity and in combination therapy with leptin, both of which warrant further investigation in future studies." (PMID 41016636, 2025). "In obesity, circulating levels of leptin increase, a phenomenon reported as leptin resistance." (PMID 40531756, 2025). "Regarding metabolic diseases and obesity in humans, the leptin system’s network is crucial." (PMID 40242447, 2025). "The imbalance between leptin and adiponectin in obesity can worsen the severity of AP." (PMID 40937420, 2025). "BMI may be a valuable consideration as obesity may affect the exercise-cognition relationship via leptin resistance; animal model work demonstrated that obesity impairs the consolidation pathways of memory." (PMID 40252111, 2025). "The ratio of BioLEP to total LEP (BioLEP/LEP) provides additional insight into LEP functionality and may help elucidate the pathophysiology of obesity." (PMID 40586327, 2025). "A cross-sectional study of 111 obese and 105 non-obese male older adults observed that irisin and leptin concentrations were associated with obesity." (PMID 39846531, 2025).
Obesity (continued). "The answer to this conundrum relies on the fact that in a hyperleptinemic state, the maximum hypothalamic leptin response is decreased, resulting in leptin resistance, and adiponectin is reduced by processes inherent to obesity, which will be discussed during this review." (PMID 40002337, 2025). "Additionally, disruptions in leptin signaling, crucial for appetite and energy balance, further exemplify the genetic underpinnings of obesity." (PMID 40428329, 2025). "Ablation of Stat3 in the CNS (or in Lepr cells) or the mutation of LepRb Tyr1138 in mice promotes hyperphagic obesity and other defects in leptin action, though these effects do not fully recapitulate the phenotype of LepRb deficiency." (PMID 40393800, 2025). "Elevated leptin levels in obesity exacerbate inflammation and diminish its neuroprotective effects." (PMID 41516046, 2025). "While monogenic nonsyndromic obesity (such as mutations in the MC4R, LEP, or POMC genes) generally presents with severe hyperphagia and weight gain in early life but otherwise normal neurocognitive development, syndromic forms typically display additional systemic or neurological features." (PMID 40689079, 2025). "Furthermore, emerging evidence indicates that gut bacteria-derived metabolites upregulate the production of pro-obesity adipokines, such as leptin, resistin, IL-6, MCP-1, and PAI-1, and downregulate the anti-obesity ones, such as adiponectin." (PMID 40699823, 2025). "Altered levels of adipokines such as leptin and adiponectin seen in MetS or obesity may also play a role in promoting Th1 and Th17 cells and inhibiting Treg and Th2 cell populations." (PMID 40696355, 2025). "Leptin, which regulates glucose homeostasis and inflammation, is elevated in obesity." (PMID 39861467, 2025). "Moreover, developing leptin resistance in obesity triggers the dysregulation of hippocampal neurotransmitter release and synaptic plasticity, resulting in AD neuropathology." (PMID 40498212, 2025). "Obesity in children with T1DM contributes to excessive leptin release." (PMID 40277935, 2025). "Moreover, here, the expressions of Lep in VAT and SAT from the BB group were completely or partially restored to those levels observed in the C group, highlighting BB as a potential fruit for controlling leptin levels in the context of obesity." (PMID 40847538, 2025). "The cloning of leptin in 1994 was an important milestone in obesity research." (PMID 40415699, 2025). "Furthermore, leptin transport across the blood brain barrier is impaired by hypertriglyceridemia, which occurs in both starvation and with the insulin resistance of obesity." (PMID 40950761, 2025). "In addition, leptin and obesity have a significant inverse relationship with FVC and FEV1 (p ≤ 0.05)." (PMID 40095561, 2025). "Elevated levels of free fatty acids and chronic overnutrition induce lipotoxicity and endoplasmic reticulum (ER) stress, triggering inflammatory responses that may contribute to a less efficient physiological response of leptin in obesity." (PMID 40531756, 2025). "Subsequent RCTs in different patient populations with obesity did not reveal a role of leptin replacement therapy in inducing weight loss." (PMID 39929239, 2025). "High leptin levels resulting from leptin resistance can be observed in individuals with obesity." (PMID 40864791, 2025). "In BED, leptin resistance often occurs, particularly in individuals with obesity." (PMID 40452002, 2025). "One member of the vanilloid TRP family, TRPV1, mediates the sensing of the carotid body to Th2 cytokines and lysophosphatidic acid, and a member of the melastatin TRP family, TRPM7, is involved in the regulation of obesity-induced hypertension mediated by leptin." (PMID 41226725, 2025). "While leptin levels increase in obesity, adiponectin levels decrease abruptly, which at first glance may seem paradoxical." (PMID 40002337, 2025).
Obesity (continued). "High LEP levels in children with obesity, and their dependence on adipose tissue content, may suggest the presence of leptin resistance related to an altered leptin receptor/post-receptor pathway in this group." (PMID 40586327, 2025). "In large population studies, serum TSH is usually positively correlated with body weight and body mass index, and elevated TSH may contribute to overweight or obesity, an effect that may be mediated in part by leptin." (PMID 40270696, 2025). "However, the elevated leptin levels in obesity can activate protumorigenic signaling pathways (JAK/STAT, MAPK, PI3K/Akt), thereby enhancing thyroid cell proliferation and invasion." (PMID 40722754, 2025). "BED independently affects 2% to 5% of non-obese individuals; however, in 30% to 90% of obese patients, this suggests that alterations in the leptin-melanocortin system may contribute to binge eating in individuals with severe obesity." (PMID 40077044, 2025). "The imbalance of adipokines secreted by adipose tissue in obesity, especially elevated leptin levels, activates inflammatory pathways such as IL-1β and NF-κB, promoting articular cartilage degradation and synovial inflammation, which is an important mechanism in the development of OA." (PMID 40964689, 2025). "In addition, other hormonal factors associated with obesity, including insulin-like growth factor 1(IGF-1), steroid hormones, AMP-activated protein kinase, and leptin, also play a significant role in the initiation and progression of BC." (PMID 40136371, 2025). "Notably, animals with mutation or dysregulation in the leptin gene can lead to hypoleptinemic obesity, and this form of obesity is responsive to leptin treatment." (PMID 41016636, 2025). "Those with leptin above the median were predominantly female (71% vs. 28%, p < 0.001) and had significantly higher adiposity measures, including BMI (28 vs. 25 kg/m2, p < 0.001) and obesity prevalence (33% vs. 6%, p < 0.001)." (PMID 40956476, 2025). "Leptin resistance limits the effectiveness of leptin therapy for obesity, but targeting leptin receptors and downstream signaling in specific brain regions may help." (PMID 41150735, 2025). "In other words, leptin is essential for controlling inflammatory responses and maintaining cardiovascular homeostasis and is thought to be involved in the increase of inflammation not only in obesity but also in cardiovascular disease and type 2 diabetes." (PMID 39897330, 2025). "Importantly, intranasal delivery appears to bypass central leptin resistance, a key obstacle in obesity treatment." (PMID 41226331, 2025). "Importantly, leptin–chronically elevated in individuals with obesity–activates the PI3K/PKC pathway, increasing ROS production and promoting a Th1-type inflammatory response, thereby further increasing OS and inflammation in adipose tissue." (PMID 40944223, 2025). "Notably, obesity-induced HPG axis dysfunction involves leptin resistance-mediated suppression of hypothalamic kisspeptin signaling, which impairs pulsatile gonadotropin-releasing hormone (GnRH) secretion." (PMID 40292466, 2025). "Individuals with obesity often exhibit elevated free leptin levels in the brain, which may contribute to the development of leptin resistance—a condition characterized by reduced sensitivity or impaired responsiveness to leptin signaling." (PMID 41439942, 2025). "Due to a lack of autophagy and poor energy regulation, leptin resistance causes obesity and metabolic diseases." (PMID 40989799, 2025). "Obesity contributes to a pro-inflammatory state that exacerbates psoriasis by secreting adipokines, such as leptin and resistin, which stimulate Th17 and Th1 cells, thereby increasing Il-17 and TNF-a cytokines, key factors involved in the pathogenesis of psoriasis." (PMID 40003621, 2025).
Obesity (continued). "In the obesity and diabetes groups, the levels of pro-inflammatory cytokines such as resistin, leptin, IL-6, and TNF-α were high, which might have expanded the mass of dysfunctional adipose tissue." (PMID 40095937, 2025). "Compared with adiponectin alone, the serum adiponectin/leptin ratio showed a higher correlation coefficient in individuals without obesity and reached statistical significance in visceral adipocytes of individuals with obesity." (PMID 41271970, 2025). "Leptin is a molecule that has anti-adiponectin effects so measurement of the adiponectin/leptin ratio may serve as a marker linking obesity and cancer." (PMID 40076851, 2025). "Interestingly, ASCs isolated from obese individuals express higher amounts of leptin relative to the same cell type isolated from lean counterparts and the increase in leptin under obesity enhances the proliferation and metastasis of breast cancer cells." (PMID 39496581, 2025). "Moreover, individuals with overweight or obesity tend to consume highly palatable foods, which enhance triglyceride synthesis and, consequently, leptin production by white adipose tissue." (PMID 41439942, 2025). "Furthermore, obesity-induced dysregulation of adipokines, including leptin and adiponectin, exacerbates metabolic imbalance by favoring insulin resistance and hyperglycemia." (PMID 41268160, 2025). "For instance, leptin has been proposed as an obesity-derived factor favoring the efficacy of ICI." (PMID 40522918, 2025). "Given that leptin levels are typically elevated in overweight and obese individuals, and that obesity is a major risk factor for insulin resistance and T2DM, it was expected that participants with youth-onset T2DM would exhibit higher leptin levels compared to those with NGT." (PMID 40630340, 2025). "By linking metabolic regulation to cognition, leptin’s role in obesity-related hippocampal abnormalities suggest that it may be the biochemical link connecting cognition and weight-gain/loss." (PMID 40607230, 2025). "However, elevated leptin levels in obesity often reflect a state of leptin resistance, compromising its physiological function." (PMID 40733199, 2025). "However, further research is needed to confirm these results and determine the underlying mechanisms responsible for the observed relationships between leptin, obesity, and biophysical parameters in type 2 diabetes mellitus patients." (PMID 41239622, 2025). "In particular, hypothalamic inhibition of IKKβ has shown striking metabolic benefit in preclinical models, restoring leptin and insulin sensitivity and preventing diet-induced obesity without causing systemic immune impairment." (PMID 41463063, 2025). "Leptin levels might contribute to such effects by regulating a chronic low-grade inflammatory state in obesity due to its function as a proinflammatory cytokine." (PMID 41338008, 2025). "The association between leptin and glucose was positive in controls, positive but reduced in patients with obesity (FDR p = 0.006) and negative in patients with T2DM (FDR p < 0.001)." (PMID 40965347, 2025). "For instance, it may suggest that T2DM patients with obesity and elevated leptin levels may benefit from interventions targeting leptin signaling to improve metabolic control and prevent renal complications." (PMID 41239622, 2025). "This suggests that a low adiponectin/leptin ratio may be a characteristic feature of obesity and MetS." (PMID 41155195, 2025). "Alterations in adipokines, such as decreased levels of adiponectin and increased levels of leptin, nicotinamide phosphoribosyltransferase (NAMPT)/Visfatin, and/or resistin, trigger abnormalities in MSC functions that promote obesity-associated illnesses and alter the response to MSC therapy." (PMID 40893809, 2025). "However, obesity induces leptin resistance, characterized by impaired BBB transport, saturated Ob-R signaling, and induction of negative regulators such as SOCS3, PTP1B, and TCPTP, often in an inflammatory milieu." (PMID 41155642, 2025).